FAR1 (fatty acyl-CoA reductase 1)
Diseases named in the same sentence as FAR1 in open-access papers:
FAR1 is named in the same sentence as 44 diseases in open-access papers, as found by Europe PMC text mining. Sharing a sentence is not in itself a finding about the gene and the disease. The quoted sentences say what the papers report.
cataract (5 papers, 2017 to 2025). Partial or complete opacity of the crystalline lens of one or both eyes that decreases visual acuity and eventually results in blindness. "For instance, recessive LOF and dominant GOF variants in FAR1 cause opposing biochemical responses but share similar clinical features, such as developmental delay, spasticity, epilepsy, and cataracts." (PMID 40299568, 2025). "Here, we report an additional case with a de novo pathogenic variant in FAR1, expanding the clinical spectrum of cataracts, spastic paraparesis, and speech delay (CSPSD)." (PMID 36254151, 2022). "However, heterozygous variants in FAR1 have been recently linked to a rare genetic disorder called cataracts, spastic paraparesis, and speech delay (CSPSD)." (PMID 36254151, 2022). "A mutation in exon 9a (p.Asp365Gly) of FAR1, a gene of the plasmalogen–biosynthesis pathway, causes rhizomelic chondrodysplasia punctata (RCDP), a disease that is characterized by severe intellectual disability with cataracts, epilepsy and growth retardation." (PMID 29242366, 2017).
peroxisomal disorder (4 papers, 2015 to 2025). "RCDP is a peroxisomal disorder caused by mutations in ether lipid (plasmalogen) biosynthesis-associated genes such as alkylglycerone-phosphate synthase (AGPS), glycerol-3-phosphate acyltransferase (GNPAT), and fatty acyl-CoA reductase 1 enzyme (FAR1)." (PMID 40943222, 2025). "RCDP is a recessive peroxisomal disease caused by variants in five genes: AGPS, FAR1, GNPAT, PEX5, and PEX7, which encode alkylglycerone phosphate synthase, fatty alcohol reductase 1, glycerone-phosphate O-acyltransferase, and the peroxisomal biogenesis factors 5 and 7, respectively." (PMID 40394457, 2025).
rhizomelic chondrodysplasia punctata (4 papers, 2017 to 2025). Rhizomelic chondrodysplasia is a form chondrodysplasia punctata, a group of diseases in which the common characteristic is calcifications near joints at birth. "Furthermore, loss-of-function mutations in four genes (PEX7, GNPAT, AGPS, and FAR1) that mediate peroxisomal synthesis of AAG, a necessary substrate for synthesis of plasmenyl-PE and plasmenyl-PC, result in rhizomelic chondrodysplasia punctata (RCDP)." (PMID 38582453, 2024).
Intellectual disability (3 papers, 2015 to 2020). "The spectrum of clinical features associated with defects in plasmalogen biosynthesis is expanded to include FAR1 deficiency as a cause of syndromic severe intellectual disability with cataracts, epilepsy, and growth retardation but without rhizomelia." (PMID 26933529, 2015).
microcephaly (3 papers, 2015 to 2025). A congenital or acquired developmental disorder in which the circumference of the head is smaller than normal for the person's age and sex. "Of interest, complete loss‐of‐function FAR1 mutations decrease the levels of plasmalogen, a type of ether phospholipids and are associated with severely delayed psychomotor development, growth retardation with microcephaly, and seizures." (PMID 39617394, 2025). "Conversely, autosomal dominant mutations in FAR1 that promote unrestrained ether lipid synthesis lead to spastic paraplegia and delayed development without microcephaly and diminished growth." (PMID 38582453, 2024).
breast carcinoma (2 papers, 2019 to 2021). "IHC staining revealed similar strong relevance of FAR1 and 4-HNE in breast cancers, indicating FAR1 participates in the process of ferroptosis in human cancers." (PMID 33731874, 2021). "Further analysis reveals the colorectal and breast cancer patients expressing higher levels of FAR1 have a significantly higher overall survival compared to patients bearing tumors expressing lower levels of FAR1 expression." (PMID 33731874, 2021). "In addition, comparing to more malignant tumor progression of T3 and T4 stage, the expression levels of FAR1 were much lower in T1 and T2 stage according to tumor nude metastasis (TNM) subsets in breast cancers." (PMID 33731874, 2021).
liver cancer (2 papers, 2021 to 2026). An epithelial or non-epithelial malignant neoplasm that arises from the liver. "Moreover, ectopic expression of FAR1 rendered the liver cancer cell lines susceptible to ferroptosis." (PMID 33731874, 2021). "Moreover, Kaplan–Meier survival analysis demonstrated that high expression of FAR1 is associated with improved overall survival in patients with other types of cancers including liver cancer, rectum adenocarcinoma and bladder carcinoma." (PMID 33731874, 2021). "As expected, IHC staining of FAR1 was highly consistent with 4-HNE staining in the human liver cancer tissue microarray." (PMID 33731874, 2021). "FAR1 protein levels were barely undetectable in liver cancer cell lines while other cancer cell lines exhibited higher FAR1 levels." (PMID 33731874, 2021). "Strikingly, TCGA gene enrichment analysis reveals that FAR1 exhibits a significantly lower enrichment in liver cancer than in other types of cancer." (PMID 33731874, 2021). "Notably, FAR1 signaling intensity is lower in liver cancer than para-cancer tissues, indicating FAR1 is a potential tumor suppressor." (PMID 33731874, 2021). "FAR1 methylation emerged as an HCC-specific biomarker, showing significantly higher levels in liver cancer cell lines and HCC tumour tissues compared with controls." (PMID 42009371, 2026).
nematode infection (2 papers, 2015 to 2022). "Compared with WT A. thaliana, transgenic lines overexpressing Ab-FAR-1Δsp were more susceptible to nematode infection, whereas Ab-far-1 RNAi lines showed the opposite trend." (PMID 36293146, 2022). "Our results indicate that roots overexpressing mj-far-1 still mount a defense response against nematode infection; however, this rapid response might reflect the accelerated disease progress in OE roots upon nematode infection." (PMID 25886179, 2015).
acute kidney injury (1 paper, 2025). Sudden and sustained deterioration of the kidney function characterized by decreased glomerular filtration rate, increased serum creatinine or oliguria. "These multi-level experimental validations collectively establish FAR1 as a potential biomarker and candidate modulator, pending further mechanistic elucidation to clarify its functional significance in context of acute kidney injury." (PMID 40827445, 2025).
Alzheimer disease (1 paper, 2021). A progressive, neurodegenerative disease characterized by loss of function and death of nerve cells in several areas of the brain leading to loss of cognitive function such as memory and language. "Previous studies indicate that plasmalogens degrades FAR1, dysregulation of plasmalogens is closely associated with cancer and neurodegeneration including Alzheimer’s disease." (PMID 33731874, 2021).
chondrodysplasia punctata (1 paper, 2022). A rare congenital developmental disorder characterized by the presence of stippled foci of calcification in the hyaline cartilage, joint contractions, mental retardation and ichthyosis. "Inherited mutations in the FAR1 gene causing reduction or complete loss of FAR1 activity result in peroxisomal FAR1 deficiency (MIM #616154, also referred to as RCDP type 4), which can be clinically distinguished from the other forms of RCDP by the absence of chondrodysplasia punctata or rhizomelia." (PMID 36120579, 2022).
colorectal cancer (1 paper, 2017). A primary or metastatic malignant neoplasm that affects the colon or rectum. "FAR1 has also been shown to be expressed differently between visceral and subcutaneous adipose tissue in colorectal cancer patients." (PMID 28417008, 2017).
infertile (1 paper, 2025). "We generated Far1 KO mice and found that male Far1 KO mice were infertile." (PMID 40288649, 2025).
ischemia (1 paper, 2025). A hypoperfusion of the BLOOD through an organ or tissue caused by a PATHOLOGIC CONSTRICTION or obstruction of its BLOOD VESSELS, or an absence of BLOOD CIRCULATION. "Future research should focus on stratifying FAR1 expression according to specific AKI causes, such as sepsis, nephrotoxin exposure, or ischemia, to determine whether FAR1 is universal biomarker or specific to particular subtypes of renal injury." (PMID 40827445, 2025).
liver fibrosis (1 paper, 2018). "Lentivirus-mediated knockdown of lnc-FAR1 in CCl4-treated mice resulted in the attenuation of liver fibrosis and reduced levels of hepatic hydroxyproline content and serum levels of alanine transaminase (ALT) and aspartate transaminase (AST)." (PMID 30134610, 2018). "Together, lnc-FAR1 was found to exert effects on HSC activation, hepatocyte apoptosis, and liver fibrogenesis in a mouse model of liver fibrosis." (PMID 30134610, 2018).
lymphoma (1 paper, 2020). A malignant (clonal) proliferation of B- lymphocytes or T- lymphocytes which involves the lymph nodes, bone marrow and/or extranodal sites. "In addition to AGPS, elevated expression of FAR1, FAR2, and GNPAT, all of which are involved in ether phospholipid biosynthesis, was observed in aggressive lymphoma cells derived from lymphoma patients who were refractory to oxidative stress-inducing therapy." (PMID 32674458, 2020).
male infertility (1 paper, 2025). The inability of the male to effect fertilization of an ovum after a specified period of unprotected intercourse. "Cgt KO and Cst KO mice exhibited a loss of seminolipids, deficient spermatogenesis with multinucleated spermatogenic cells, and male infertility; phenotypes similar to those in Far1 KO mice." (PMID 40288649, 2025). "Far1 KO mice exhibited a loss of seminolipids in the testes, reduced numbers of spermatogenic cells and impaired spermatogenesis in the seminiferous tubules, reduced testicular weights, an absence of sperms in the epididymides, and male infertility." (PMID 40288649, 2025).
Obesity (1 paper, 2017). Accumulation of substantial excess body fat. "Of these GPGE association results, BARX1, ZNF169 and FAR1 were all significant in brain regions, which is consistent with a popular hypothesis that the central nervous system regulation of energy balance plays a major role in the development of obesity." (PMID 28417008, 2017).
onchocerciasis (1 paper, 2009). Onchocerciasis is a form of filariasis, caused by the parasitic worm Onchocerca volvulus, transmitted by the black fly. "In detecting onchocerciasis, the most informative antigen was Ov-FAR-1, followed by Ov-API-1, Ov-MSA-1 and lastly Ov-CPI-1." (PMID 19436728, 2009).
pancreatic cancer (1 paper, 2018). "In pancreatic cancer, the transition between IOIPMN to IPMC includes the following genes: FAR1, CEACAM1, HCCS." (PMID 33265245, 2018).
renovascular hypertension (1 paper, 2025). High blood pressure secondary to renal artery stenosis. "In renovascular hypertension models, cortical FAR1 expression decreased compared to sham-treated controls." (PMID 40827445, 2025).
type 2 diabetes (1 paper, 2017). "Further, variants near FAR1 (fatty acyl-CoA reductase 1) have been previously associated with bone mineral density in Hispanic children, and BCL9 has recently been identified with type 2 diabetes in aboriginal Australians." (PMID 28417008, 2017).
cancer (8 papers, 2018 to 2025). A tumor composed of atypical neoplastic, often pleomorphic cells that invade other tissues. "Our findings from cancer cell line studies prompted further analysis of FAR1 function in ferroptosis-associated pathological conditions in vivo." (PMID 33731874, 2021). "Taken together, these findings demonstrate the specific requirement of FAR1 for ferroptotic cell death in cancer cells." (PMID 33731874, 2021). "To further validate these findings, we examined FAR1 protein levels in a variety of human cancer cell lines." (PMID 33731874, 2021). "Notably, RSL3-induced ferroptosis was almost completely abolished in these cancer cell lines with low abundant FAR1." (PMID 33731874, 2021). "Western blot analysis showed that FAR1, FAR2, and AGPS protein expression was consistently enhanced in all cancer cell lines compared to primary cells, although these differences were statistically different in all tumor cell lines simultaneously only for FAR1." (PMID 32443825, 2020). "FAR1 mRNA levels were uniformly overexpressed in all cancer cell lines by 5.6-fold (average value)." (PMID 32443825, 2020). "Remarkably, cancer cells with highly saturated lipids require genes involved in peroxisome ether phospholipid synthesis, such as AGPS and FAR1, for their growth." (PMID 32674458, 2020). "Cancer cells may evade ferroptosis by downregulating enzymes such as AGPS and FAR1, leading to a significant reduction in vulnerable polyunsaturated ether phospholipid species." (PMID 40647540, 2025). "According to our results, the increase in PE plasmalogens could be explained by overexpression of the key plasmalogen synthesis enzymes, FAR1, FAR2, and AGPS, in all cancer cell lines." (PMID 32443825, 2020). "Interestingly, FAR1 and FAR2 were overexpressed in all cancer cells compared to primary cells, at rather similar levels for each cancer cell type (8- to 10-fold in Colo 201; 12-fold in HT29; 5-fold in LS174 and 8- and 12-fold in SW480)." (PMID 32443825, 2020).
infection (8 papers, 2013 to 2025). The state of being infected such as from the introduction of a foreign agent such as serum, vaccine, antigenic substance or organism. "To further understand the role of these FARs in infection, we analyzed data from previous studies and found that Hp-FAR-1 was identified as the third-most abundant FAR in adult HES and the most abundant FAR in L4 larvae, across three separate studies." (PMID 40501701, 2025). "To understand the role of Hp-FAR-2 in infection, we investigated the genome of H. polygrus and found it to encode for six FARs, including Hp-FAR-2 and Hp-FAR-1." (PMID 40501701, 2025). "Real-time quantitative PCR results showed that the expression level of the Ab-far-1 gene was significantly decreased by 86.65% and 87.57% upon infection of the RNAi5 and RNAi8 lines, respectively, compared with nematodes from WT (p < 0.05)." (PMID 36293146, 2022). "FAR-1 and 2 seem to have similar in vivo effects, at least at the level of the outcome of infection, leading us to believe that downstream immune effects are also being affected in similar ways not specific enough to evaluate their differences." (PMID 34714893, 2021). "Recombinant FAR-1 and FAR-2 were co-injected into adult flies, mimicking an EPN infection with delivery of the protein and pathogenic bacteria into the hemocoel." (PMID 34714893, 2021). "The expression of far-1 was shown to be highest in the females of the migratory parasites R. similis and A. besseyi because the females are responsible for infection and reproduction." (PMID 25734501, 2015). "In addition to a one-time injection of recombinant of FAR-1 and FAR-2, we also determined the outcome of infection using transgenic flies expressing either FAR-1 or FAR-2." (PMID 34714893, 2021). "The results indicated that FAR-1 & 2 have measurable differences in binding specificity, suggesting that they may target different lipid signaling molecules during infection." (PMID 34714893, 2021). "Meanwhile, Ab-far-1 in the hypodermis may help nematodes to neutralize plant defense and to complete the infection." (PMID 23755297, 2013). "After injection with 1,000 cells of L. monocytogenes, FAR-1 and FAR-2 expressing flies were unable to initiate PO activity six hours post-infection." (PMID 34714893, 2021). "FAR1 DNA binding domain which contains a WRKY-like fold and probably a zinc finger DNA-binding domain has been found only in S-PI and R-PI library contigs revealing its counteractive role during pathogen infection." (PMID 26840746, 2016). "We conclude that FAR1 and FAR2 are not necessary for infection-associated lipid body mobilisation in M. oryzae, which is instead dependent on autophagy." (PMID 24949933, 2014). "This might indicate that Ab-FAR-1 without a signal peptide was secreted by nematodes and acted on the cytoplasm and nucleus of the host during RWTN infection." (PMID 36293146, 2022).
tumor (6 papers, 2019 to 2026). "have shown that ether lipid plasticity driven by FAR1 increases ferroptosis susceptibility in tumor cells." (PMID 40827445, 2025). "Considering tissue-specific lipid metabolism and ferroptotic regulation, FAR1-ferroptosis relationship might behave differently in renal tissues compared to tumor contexts." (PMID 40827445, 2025). "Since FAR1 is essential for ether lipid generation which sensitizes the cells to ferroptosis, we then sought to determine whether FAR1 functions as a tumor suppressor by activating ferroptotic responses." (PMID 33731874, 2021). "Taken together, these data demonstrate that FAR1 is positively correlated with ferroptosis responses in renal IRI and tumors, implying a potential role of FAR1 as a tumor suppresser via ferroptosis." (PMID 33731874, 2021). "Several of the understudied genes are directly involved in critical metabolic pathways of tumor etiology, including glucose metabolism (SORD), lipid biosynthesis (FAR1), cAMP signaling pathway (PDE7A, ADCY6), and glutamate anaplerosis (ABAT, GLUD1)." (PMID 31231467, 2019).
neurological disease (2 papers, 2017 to 2018). "A rare autosomal recessive neurological disease without hair abnormalities was reported for humans with mutations in FAR1." (PMID 28700664, 2017).
bacterial infection (1 paper, 2021). "To establish the mechanism by which FAR-1 and FAR-2 elicit their immunomodulatory effects, we evaluated several readouts of immunity including phenoloxidase (PO) activity and melanization, which are essential immune defenses during a bacterial infection." (PMID 34714893, 2021).
FAR1 also shares sentences with these, for which no sentence is quoted: epilepsy (3 papers); bladder carcinoma (1); colon cancer (1); congenital cataracts (1); developmental delay (1); diffuse large B-cell lymphoma (1); early-onset epilepsy (1); genetic disorder (1); hepatocellular carcinoma (1); paraplegia (1); parasitic infection (1); rectum adenocarcinoma (1); Rhizomelia (1); rhizomelic chondrodysplasia punctata type 1 (1); Sepsis (1); Spastic paraparesis (1); Spasticity (1).